DRD2 (dopamine receptor D2)
Diseases named in the same sentence as DRD2 in open-access papers (continued):
Sharing a sentence is not in itself a finding about the gene and the disease.
autism (11 papers, 2012 to 2025). Persistent deficits in social interaction and communication and interaction as well as a markedly restricted repertoire of activity and interest as well as repetitive patterns of behavior. "The role of the DRD2 gene in autism susceptibility was suggested by the fact that antipsychotic medications, which prevent dopamine D2 receptor activation, improve the core symptoms of ASDs." (PMID 24453887, 2013). "A role for the DRD2 gene in autism susceptibility is suggested by the fact that antipsychotic medications, which prevent dopamine D2 receptor activation, improve the core symptoms of ASDs." (PMID 22559203, 2012). "To identify potential molecular biomarkers underlying autistic-like behaviors in Drd2-KO mice, we investigated Drd2-associated functional players from the Simons Foundation Autism Research Initiative (SFARI) gene database, a comprehensive resource that compiles ASD genes." (PMID 40164687, 2025). "Additional families informative at these DRD2 loci are needed to determine whether these functional variants or another functional polymorphism in LD with rs1800498 is responsible for the increased risk for autism." (PMID 22559203, 2012). "The genes within this subnetwork were enriched for Drug targets in autistic disorder and Drd2 expression targets." (PMID 40963920, 2025). "The Holden lab has found DA-related genes (DRD1, DRD2, and PPP1R1B) associated with the severity of autism in families with males only affected." (PMID 24391541, 2013). "Association studies implicate the A1 allele of the Taq1 polymorphism of DRD2 in the development of Tourette’s syndrome, ADHD, autism, PTSD, and alcoholism." (PMID 24391541, 2013). "This work aims to study the association between autism and MAOA uVNTR, MAOB rs1799836, and DRD2 TaqI A. Also the study analyzed genomic sequence variations of miR-431 and miR-21." (PMID 24453887, 2013). "This work studied the association of autism with genetic variations in neurotransmitter-related genes, including MAOA uVNTR, MAOB rs1799836, and DRD2 TaqI A in 53 autistic patients and 30 healthy individuals." (PMID 24453887, 2013). "Our findings support a role for the DRD2 and PPP1R1B genes in conferring risk for autism in families with only affected males and show an additive effect of these genes towards prediction of affected status in our families." (PMID 22559203, 2012). "Downregulation of DRD2 has been shown to activate AKT-mTOR (mammalian target of rapamycin) signaling 41,42, and activation of mTOR signaling has been implicated in the deficient synaptic pruning in the autism-spectrum diseases." (PMID 34750364, 2021). "There are two previous studies which examined the DRD2 gene as a candidate gene for autism." (PMID 22559203, 2012). "The QTDT results support an association of the DRD2 and PPP1R1B loci with autism." (PMID 22559203, 2012). "We also found that 97% of individuals from our comparison cohort and 13% of individuals with autism were correctly classified while 72% of control individuals and 64% of affected individuals were predicted correctly using a weighted additive combination of DRD2 and PPP1R1B genotypes." (PMID 22559203, 2012). "Following our findings with the DRD1 gene, and as part of our investigation to determine whether other DA-related genes are significant factors in the etiology of ASDs, we found evidence for association of the DRD2 and PPP1R1B genes with autism in affected males from multiple-incidence families." (PMID 22559203, 2012).
colorectal cancer (11 papers, 1994 to 2025). A primary or metastatic malignant neoplasm that affects the colon or rectum. "A previous study reported that some mutations in the DRD2 gene were associated with colorectal cancer." (PMID 33692961, 2021). "We have examined a series of human colorectal adenomas, carcinomas and cell lines derived from human colorectal cancer for loss of heterozygosity (LOH) on chromosome 11q22-23 by polymerase chain reaction (PCR) amplification of a microsatellite polymorphism of the dopamine D2 receptor (DRD2) locus." (PMID 8080720, 1994). "The DRD2 antagonist thioridazine (THIO) exerts antitumor effects in colorectal cancer." (PMID 38494840, 2024). "Additionally, our predictions point to promising strategies such as targeting DRD2 for tumor suppression and validating Olsalazine and Pizotifen for colorectal cancer through their effects on Wnt signaling and COX1." (PMID 39273521, 2024). "Interestingly, a recent preclinical study investigating the efficacy of the DRD2 antagonist Trifluoperazine (TFP) in colorectal cancer reported that tumors from TFP‐treated mice had increased tumor expression of PD‐L1, as well as increased PD‐1 expression on tumor‐infiltrating CD4+ and CD8+ T cells." (PMID 38572507, 2024). "Transient knockdown of DRD2 in colorectal cancer cells minimally affected response to ONC201, further indicating DRD2 antagonism may not be the cause of imipridone cytotoxicity." (PMID 41008904, 2025).
eating disorder (11 papers, 2015 to 2026). A broad group of psychological disorders with abnormal eating behaviors leading to physiological effects from overeating or insufficient food intake. "Dopamine receptor D2 (DRD2) gene encodes a G-protein-coupled dopamine receptor, which inhibits adenylyl cyclase activity and eating-related psychological traits in eating disorders." (PMID 36297109, 2022). "Thus, we believe that miR-504 and miR-16 modulate DRD1 and DRD2, in the context of eating disorders associated with ELS." (PMID 32848865, 2020). "Groleau and colleagues reported higher methylation of the DRD2 promoter in women with an eating disorder and a history of childhood trauma versus those without such a history." (PMID 31780969, 2019). "Moreover, women with a history of bulimia spectrum disorder and childhood sexual abuse showed increased DRD2 DNA methylation compared to the group with no eating disorder history." (PMID 38766604, 2024).
heroin dependence (11 papers, 2007 to 2025). Physical and psychological dependence on the drug heroin. "This case-control study reported a relationship between DRD2 and the potential risk of developing heroin dependence." (PMID 23840506, 2013). "Conflicting associations with heroin dependence have been found involving the A1 allele of dopamine D2 receptor gene (DRD2) TaqI A polymorphism." (PMID 17543096, 2007). "The present case-control study shows that DRD2 contributes to the variation in the risk for heroin dependence in Spanish individuals." (PMID 17543096, 2007). "The aim of the present study was to examine the association of heroin dependence with DRD2 A1 alleles in Spanish subjects of European origin." (PMID 17543096, 2007). "The study was aimed to examine the association of heroin dependence with the DRD2 TaqI A polymorphism in Spanish subjects of European origin." (PMID 17543096, 2007). "Our results indicate that, in Spanish individuals, genotypes of the DRD2 TaqI A polymorphism contribute to variations in the risk of heroin dependence, while single alleles contribute only in males." (PMID 17543096, 2007). "Using data from a study of association between heroin dependence and the DRD2 gene, we obtained estimated haplotype frequencies and the associated likelihood ratio statistic using two different computer programs, MLOCUS and GENECOUNTING." (PMID 17597526, 2007). "Their findings indicated a role for DRD2 polymorphism in heroin dependence in the Chinese Han population and may be helpful for future genetic or neurobiological studies on heroin dependence." (PMID 30542299, 2018). "Based on these results we hypothesized that it is rather a DRD2 than an ANKK1 gene variant which has a direct effect on heroin dependence." (PMID 23840506, 2013). "Both features could maximise a study's ability to detect genetic associations: with non-opioid substance use, because it is also related with the DRD2 A1 allele; and with methadone treatment, because it can be a marker of heroin dependence severity." (PMID 17543096, 2007). "Additional systems biology results indicated heroin dependence as the highest-risk manifestation linked to these genes, and PGx analyses suggested DRD1, DRD2, BDNF, and OPRM1 as promising targets for future studies." (PMID 41333412, 2025). "Other studies from Yale University showed that a haplotype block of the DRD2 gene A1 allele was associated with AUD and heroin dependence." (PMID 37560184, 2023). "As a result, the applied Bayesian method confirmed the relevance of DRD2 TaqIB SNP in heroin dependence and revealed a new interaction partner in the DRD4 promoter, the −615 A/G SNP modulating through the −521 C/T SNP." (PMID 23840506, 2013). "This study found that genetic polymorphisms, specifically rs1799732 (C/-C), within DRD2 gene play a role as a susceptibility gene with heroin dependence in Chinese but not in German population." (PMID 22963930, 2012). "According with our results, the A1-A1 genotype of the DRD2 TaqI A polymorphism is associated with heroin dependence regardless of gender, while the A1 allele is associated with heroin dependence only in males." (PMID 17543096, 2007). "The gene coding for the dopamine receptor D2 (DRD2) could be involved in heroin dependence and other SUD as a nonspecific genetic factor, because opioids and other substances of abuse induce some of their rewarding effects through the mesolimbic dopamine system." (PMID 17543096, 2007).
Hyperglycemia (11 papers, 2020 to 2025). An increased concentration of glucose in the blood. "In conclusion, these results suggest that the protein expression of DRD2 in SAT is up-regulated with hyperglycemia and T2D." (PMID 37752366, 2024). "The results suggest that protein expression of DRD2 in subcutaneous adipose tissue is up-regulated with hyperglycemia and T2D." (PMID 37752366, 2024). "Accordingly, DRD2 protein expression positively correlated with hyperglycemia markers." (PMID 37752366, 2024).
lung carcinoma (11 papers, 2018 to 2025). "DRD2 is implicated in lung cancer, and DRD2 agonists demonstrate significant growth inhibition in both NSCLC and SCLC." (PMID 36072788, 2022). "Three SNPs: rs1799732, rs5744256, and rs2306022 from DRD2, IL-18, and ITGA11 were among the five SNPs that MDR selected as best associated with lung cancer." (PMID 38137497, 2023). "In lung cancer, overexpressed DRD2 or treatment with its agonist resulted in the inhibition of cancer progression." (PMID 36428628, 2022). "We also showed that DRD2 expression in tumors of lung cancer patients demonstrates a positive correlation with the extent of cigarette smoke exposure and the histological grade of the tumor." (PMID 36072788, 2022). "Although our study suggests a probable connection of DRD2 with nAChR and PD-L1 in lung cancer for the first time, there are several limitations in our study." (PMID 36072788, 2022). "The objective of this study is to evaluate the expression of different nicotinic acetylcholine receptors (nAChRs), programmed death ligand-1 (PD-L1), and dopamine receptor D2 (DRD2) as prognostic factors in lung cancer and any correlation among them." (PMID 36072788, 2022). "Conversely, it has been revealed that DRD2 agonist has inhibitory properties in several cancer types, such as lung cancer, gastric cancer, prostate cancer, and leukemia." (PMID 34952904, 2021). "Dopamine receptor antagonists primarily targeting DRD2 inhibited TIC growth in lung cancer and leukemia." (PMID 33945569, 2021). "In mouse models of lung cancer, Dopamine receptor D2 (D2R) agonist inhibits angiogenesis." (PMID 36980690, 2023). "Importantly, the expression levels of the DRD2 nano drug-treated QU-DB lung cancer cell line were significantly higher compared to the A549 lung cancer cell line." (PMID 34952904, 2021). "Also, the expression levels of DRD2 in BRC-treated lung cancer cell lines were significantly higher compared to treated or untreated MRC5 normal cell lines." (PMID 34952904, 2021). "DRD2 and DRD4 receptors were significantly higher than other DRDs in treated (free BRC and MWCNTs-BRC Nf) lung cancer cell lines compared to untreated groups." (PMID 34952904, 2021). "In this research, after treatment of lung cancer cells with BRC, high expression levels of DRD2 were found and at a low dosage of the drug in conjugated form, this effect was found to be stronger while having more potent anti-cancer effects and less toxicity." (PMID 34952904, 2021).
neuroblastoma (11 papers, 2014 to 2025). Neuroblastoma (NB) is the most common solid, extracranial childhood tumor. "As H2O2 exposure up-regulates DRD2 in the human SH-SY5Y neuroblastoma cell line through NF-κB nuclear translocation, PA-C treatment may downregulate DRD2 expression by inhibiting the NF-κB signaling pathway." (PMID 34073117, 2021). "On that note, our research team has previously reported that the SH-SY5Y neuroblastoma cells differentiated in RA containing low serum medium for 6 days significantly enhanced the dopamine and α-synuclein levels besides upregulating the dopamine receptor D2 (DRD2) gene expression." (PMID 35258800, 2022). "TRF pre-treatment in 6-OHDA-induced neuroblastoma cells ↑ cell viability, ↓ ROS generation and CAT activity, ↑ SOD activity, and ↑ dopamine receptor D2 gene expression compared to the untreated groups (treated with 6-OHDA without TRF supplementation)." (PMID 40869012, 2025).
Tourette syndrome (11 papers, 2009 to 2026). A neurologic disorder caused by defective metabolism of the neurotransmitters in the brain. "Meta-analysis of the association between the DRD2 Taq I A polymorphism and Tourette syndrome." (PMID 26110876, 2015). "In the Tourette syndrome group and in smokers there was a significant additive effect of the DRD1 and DRD2 genes." (PMID 22408582, 2011). "Polymorphisms of three different dopaminergic genes, DA D2 receptor (DRD2), DBH, and DA transporter (DAT1), were examined in Tourette syndrome probands, their relatives, and controls." (PMID 22408582, 2011).
anxiety disorder (10 papers, 2015 to 2024). A category of psychiatric disorders which are characterized by anxious feelings or fear often accompanied by physical symptoms associated with anxiety. "The interaction of ADORA2A and DRD2 genes has been reported to be responsible for anxiety disorders in ADHD children and adolescence." (PMID 36211978, 2022). "Interestingly, phenothiazines are widely used as DRD2 antagonists in anxiety disorders, and DRD2 inhibitors can have a therapeutic effect on tumor-bearing mice under pressure stimulation." (PMID 40226707, 2024).
melanoma (9 papers, 2015 to 2025). A malignant, usually aggressive tumor composed of atypical, neoplastic melanocytes. "Phenothiazines induce apoptosis in a B16 mouse melanoma cell line and attenuate in vivo melanoma tumor growth or the small DRD2/3 binding molecule ONC201, which induces anticancer effect mediated by activation of the death ligand TRAIL in tumor." (PMID 35053262, 2022). "In contrast, TAAR6, TAAR8, and TAAR9 were expressed in 12.7%, 11.3%, and 5.3% of tumor specimens, respectively, so their expression is comparable with DRD2, of which expression and activity are well established in melanoma." (PMID 35053262, 2022). "As TAAR1 is coexpressed and heterodimerizes with DRD2, and can manifest its physiological effects in the brain despite its low presence, these receptors may also be prospective therapeutic targets in melanoma." (PMID 35053262, 2022). "Following mined data, all dopamine receptors were detected in melanomas; among them DRD1 in 33.8%, DRD2 in 11.3%, DRD3 in 4.5%, DRD4 in 62.4%, and DRD5 24.1% of samples." (PMID 35053262, 2022). "TAAR8, TAAR9, DRD1, DRD2, and DRD5 expression was also slightly upregulated in melanomas after immunotherapy (Padj < 0.05)." (PMID 35053262, 2022). "DRD2, DRD3, DRD5, and all identified TAARs were significantly downregulated in melanomas compared to nevi samples with the most drastic changes noted in TAARs (p < 0.05)." (PMID 35053262, 2022). "High DRD2 protein expression on tumour cells was observed in 48% of pheochromocytomas, and DRD1 expression ranged from 14% in melanoma to 57% in renal cell carcinoma." (PMID 31478179, 2020). "DRD1 and DRD2 are expressed in melanoma samples and nondamaged human skin." (PMID 35053262, 2022). "The remaining five receptors (DRD2, FZD4, GPR143, GPR161, and SMO) may be of interest in the context of melanoma, but they have not been studied yet." (PMID 35158973, 2022).
prolactinomas (9 papers, 2017 to 2025). "The LFS-associated recurrent prolactinoma was predictably resistant to the usual management by dopamine agonists not only due to its large size, elevated Ki-67 proliferation index and clinical relapse, but also to lack of expression of dopaminergic receptors, including D2, encoded by the DRD2 gene." (PMID 35978432, 2022). "Additionally, molecular markers including DRD2 gene variants, altered expression levels of PRDM2, Filamin A, or PRB3, and dysregulated TGF-β1/Smad3 signaling pathways offer insights into the molecular pathogenesis of aggressive prolactinomas." (PMID 41013821, 2025).
neuroendocrine tumors (8 papers, 2019 to 2025). "However, increased expression of DRD2 in a neuroendocrine tumor patient was associated with longer survival, and activation of DRD2 by the DRD2 agonist BIM53097 reduced the ability of migration and invasion of human tumorous pituitary cells." (PMID 35372029, 2022). "A phase II clinical trial of ONC201, a DRD2 antagonist, in human patients with metastatic neuroendocrine tumors including PPGL showed clinical benefit in the majority of patients with PPGL (5 partial responses, 7 stable diseases, 2 progressive diseases)." (PMID 37691636, 2023). "When evaluating the associations between FAM159B and typical neuroendocrine tumour markers, positive associations were observed between the IRS values of FAM15B and those of the dopamine receptor D2, SST1, SST2, SST3, SST5, CXCR4 and PD-L1." (PMID 34830137, 2021). "ONC201 is a dopamine receptor inhibitor, DRD2, and is being evaluated as phase 2 clinical trial in neuroendocrine tumors including PHEO/PGLs [ClinicalTrials.gov Identifier: NCT03034200]." (PMID 30854332, 2019).